NRP1 (neuropilin 1)
Diseases named in the same sentence as NRP1 in open-access papers (continued):
Sharing a sentence is not in itself a finding about the gene and the disease.
tumor (continued). "Consequently, H2K-P (and most other -KHHK-containing peptides) requires limited enzymatic digests to expose the C-terminal carboxyl groups for NRP-1-mediated polyplex uptake into the tumor." (PMID 39683699, 2024). "Our study establishes SEMA3A as an inhibitor of effector CD8+ T cell tumour infiltration, suggesting that blocking NRP1 could improve T cell function in tumours." (PMID 38609390, 2024). "Subsequently, the fragments bind to neuropilin-1, promoting deeper penetration into the tumor." (PMID 39518096, 2024). "A potential concern is that an iRGD-induced tumour-blood transport may enhance tumour metastasis, in particular as NRP-1 is known to have tumour-progressive effects such as stimulation of migration and angiogenesis." (PMID 38889481, 2024). "Moreover, based on animal data, the angiogenic tumor endothelium expresses elevated levels of NRP-1." (PMID 39683699, 2024). "Several reports link increased NRP1 expression in tumours to a poor prognosis for survival." (PMID 39668325, 2024). "Also, the levels of both circulating NRP-1 and tumor tissue expression of NRP-1 increase in advanced nodal and metastatic breast cancer compared to local disease." (PMID 38468231, 2024). "Notably, HPrEC cells, a non-tumoral prostate epithelial cell line, demonstrated a remarkable increase in NRP1 mRNA expression when cultured on substrates mimicking tumor-like stiffness (80 kPa)." (PMID 38903533, 2024). "Because SEMA3A mainly binds to these effector and tumor-specific T cells, this inhibitory mechanism is particularly important, and indicate that therapeutic avenues, for example use of antagonistic NRP1 antibodies, could improve anti-tumor immunity." (PMID 38609390, 2024). "Conversely, PlGF also transmits survival signals to tumor cells directly through Nrp1." (PMID 38816706, 2024). "A tumor-penetrating peptide targeting neuropilin-1 (NRP-1) was conjugated to the tetrahedron." (PMID 38531786, 2024). "Blockade of NRP1 might promote the generation of long‐lived T cells specific to tumour antigens, which are crucial for sustained anti‐tumour immune responses." (PMID 39169517, 2024). "Previous studies have shown that the cell-penetrating ability of peptides is dependent on the regulation of neuropilin-1 (NRP1), a protein that is overexpressed in cancer cell membranes and that NRP1-targeted peptides can efficiently penetrate deeper into tumor tissues and enter cancer cells." (PMID 39464634, 2024). "High GAPVD1 and NRP-1 expression correlated with lymph node metastasis and tumor size in TNBC." (PMID 38169627, 2024). "Tumor-associated CAMs downregulated CD163 and upregulated CD304 (encoded by NRP1)." (PMID 38123840, 2024). "Besides, tolerogenic tumor-associated DCs express IDO (indoleamine 2,3 dioxygenase), PD-L1, or semaphorin-4a (the ligand for Nrp1) to resist the inflammation-induced reprogramming of Tregs in vivo." (PMID 39227959, 2024). "Indeed, mice with a TAM-specific deletion of NRP-1 resulted in slower tumor growth, reduced tumor vascularity, and increased survival." (PMID 39857591, 2024). "NRP1 antagonist also enhanced the tumor cell sensitivity toward CDDP, paclitaxel, and 5-FU." (PMID 38741195, 2024). "There is a growing interest in NRP1 in the context of T cell anti-tumor immunity." (PMID 38609390, 2024). "It has become clear that NRP1 is expressed on dysfunctional tumor-specific CD8+ T cells, indicating that the protein might play an important role in regulating CD8+ T cells as well." (PMID 38609390, 2024). "NRP1 interacted with integrin-b1 to stimulate the adhesion of tumor cells to matrix proteins." (PMID 38741195, 2024). "Removal of Nrp-1 expression in Tregs prevents their recruitment to the tumor locus, thereby delaying the growth and progression of tumors, which could be reinstated by transferring Nrp-1+ Tregs adoptively from WT mice." (PMID 39227959, 2024). "Moreover, iRGD can also act as a tumor-penetrating peptide, binding to the neuropilin-1 (NRP-1) receptors on tumor cells." (PMID 39065547, 2024).
tumor (continued). "NRP1 can drive tumor progression by activating the RAS-MAPK pathway via EGFR and PDGFR." (PMID 38728245, 2024). "Additionally, VEGFA and Sema 3 A released by tumor cells can activate NRP1, which in turn triggers VEGFR1 activation and enhances TAM recruitment in gliomas." (PMID 39068459, 2024). "Furthermore, several studies have shown that NRP1 mediates signalling pathways regulating pathological vascular growth in ocular neovascular diseases and tumour development." (PMID 38323651, 2024). "Since angiogenesis and its complex pathways are crucial for tumor development and metastasis, both NRP-1 and PlGF may be attractive treatment targets in the future." (PMID 38468231, 2024). "Despite unaltered primary tumour growth, NRP1 depletion may be a promising strategy for durable anti‐tumour immunity." (PMID 39169517, 2024). "Of note, endogenous CD4+CD25+FoxP3+ T cells found within the tumor expressed both NRP1 and Plexin-A1 as well as TGFβR1-2, indicating that this subset of T cells might be modulated differently from CD8+ T cells." (PMID 38609390, 2024). "Importantly, unlike integrins that are expressed in specific cancer types, NRP-1 expression is enhanced in the majority of tumor types." (PMID 39594723, 2024). "Finally, to clarify the mechanisms of action of YAP/TEAD4/NRP1, we created xenograft tumor SCID mice." (PMID 39187525, 2024). "VEGFR-2 and neuropilin-1 are highly expressed by endothelial and tumor cells." (PMID 37280670, 2023). "NRP1 can modulate tumor resistance to different modalities of therapy." (PMID 37894289, 2023). "In addition to directly regulating cancer cell function and angiogenesis, NRP1 can interact with different components of the tumor microenvironment." (PMID 37894289, 2023). "NRP-1 plays a pivotal role in tumorigenesis and is highly expressed within tumor cells." (PMID 37896211, 2023). "Moreover, NRP1 is not only important for the intrinsic stability of Treg cells in the tumor microenvironment but also significantly inhibits the anti-tumor function of CD8+ T cells." (PMID 36841806, 2023). "Although they are not strongly correlated with tumor mutation burden (TMB) or microsatellite instability (MSI), ADIPOR1/2 genes display a significant association with cancer stemness, tumor immune microenvironment, immune checkpoint genes (especially CD274 and NRP1), and drug sensitivity." (PMID 36896172, 2023). "NRP-1 is highly expressed in tumor vascular endothelial cells and some tumor cells." (PMID 36902076, 2023). "RPL is the minimal structural part of CPQPRPLC, a peptide obtained via phage display-library screening that binds both VEGFR-1 (vascular endothelial growth factor) and NRP-1 (neuropilin-1), two essential contributors to angiogenesis whose inhibition can lead to a decrease in tumor size." (PMID 37896211, 2023). "U87MG GBM tumor xenografts overexpressing NRP1 show increased tumor growth and angiogenesis." (PMID 37894289, 2023). "In this study, we combine in silico and in vivo experiments to ascertain the putative relationship between the binding of the TPP to NRP-1 and the antitumoral effect of the tumor-penetrating and interfering peptides iRGD-IP and Lin TT1-IP in xenograft models of breast cancer." (PMID 37111665, 2023). "This would be highly useful because neuropilin-1 has recently been associated with pro-tumorigenic rather than anti-tumor processes." (PMID 36672243, 2023). "Second, the tumor immune microenvironment promotes tumor angiogenesis; neuropilin-1 can be transferred from DCs to T cells during the interaction between T cells and DCs, and the transferred neuropilin-1 can effectively bind VEGF secreted by DCs to boost tumor angiogenesis." (PMID 37727216, 2023). "Furthermore, gene deletion of Neuropilin-1 (Nrp1) in TAMs reduces their pro-angiogenic and immunosuppressive functions, resulting in a reduction in tumor growth and metastasis." (PMID 37666809, 2023).
tumor (continued). "However, microglia with downregulated Nrp1 can lead to reduced tumor neovascularization, preventing BMDMs from infiltrating the tumor and eventually reasserting a dominant position." (PMID 37700840, 2023). "Lenvatinib suppresses autophagy by inhibiting NRP1 expression in HCC cells; however, although co-treatment with bafilomycin A1 reduces the anti-tumor effect of lenvatinib, silencing the NRP1 gene can also reduce the efficacy of lenvatinib even in the presence of bafilomycin A1." (PMID 36769116, 2023). "Among the most interesting biological findings, we further affirm that neuropilin-1 might be a novel biomarker of anti-tumor and/or cytotoxic neutrophils early during immunogenic cell death in BC." (PMID 36672243, 2023). "Furthermore, an in vivo study of CSC skin papillomas highlighted how anti-VEGFR2 antibodies in combination with NRP1 deletion prevented tumor metastasis and decreased tumor size through impairing CSC stemness properties." (PMID 37305676, 2023). "The current knowledge on NRP1 expression in cancer provides an early step indicating that the potential of NRP1 as a biomarker should be further investigated in large tumor cohorts with special attention to the possible differences among distinct molecular subgroups within each tumor type." (PMID 37894289, 2023). "Additionally, tumor cells expressing elevated levels of the reported CSC markers NRP1, IGF1R, CD44, and PROM1 (CD133) were scattered across several clusters." (PMID 37966117, 2023). "These experiments also involved the modification of exosome membranes using iRGD peptides, which can enhance extravasation and targeted infiltration by interacting with integrin αvβ3 or αvβ5 and neuropilin-1 present on tumor vascular endothelium and tumor cells." (PMID 37631256, 2023). "Nrp-1 is predominantly expressed by endothelial, tumor and immune cells." (PMID 38019895, 2023). "NRP1 expression was associated with tumor cells rather than tumor vessels and increased with grade in the tumor vessels." (PMID 37894289, 2023). "The neuropilin-1(Nrp-1) is used as a precursor receptor molecule to prohibit the entry of TAMs into the hypoxic region by inhibiting the migration towards its ligand Sema3A, which can help to restore anti-tumor immunity." (PMID 37445721, 2023). "A 2019 article reported that the VEGF/NRP1 axis can inhibit tumor growth and metastasis in ccRCC." (PMID 37263638, 2023). "We hypothesized that CTSK was involved in angiogenesis and stromal remodeling in tumor tissue, and similarly, NRP1 induced epithelial-mesenchymal transition (EMT) by promoting GC metastasis via activating PI3K/Akt signaling pathway." (PMID 37930479, 2023). "In the xenograft mice model, the sh-NRP1 group had slower tumor growth compared with the NC group." (PMID 36841806, 2023). "NRP-1 is overexpressed in the tumor vasculature and in a variety of malignant cells." (PMID 37111665, 2023). "Tumor development, progression, and therapy options have all been examined for NRP-1." (PMID 35052853, 2022). "With both viruses being highly involved in carcinogenic processes, it is assumed that they compete with endogenous VEGF ligands for the binding to NRP1 and might trigger cell signalling to promote the formation of tumour vessels in cancer tissues." (PMID 35955539, 2022). "Additionally, subgroup analysis was also carried out to solve heterogeneity in the meta-analysis of NRP1 overexpression and tumor pathogenesis." (PMID 35884516, 2022). "Neuropilin-1 (NRP-1) is a multifunctional receptor that is expressed in different human cancerous tissues, including the GBM, and its expression level is associated with tumor growth." (PMID 35090496, 2022). "The investigators further reported that tumor associated macrophages lacking Nrp1 did not traffic into hypoxic areas." (PMID 36203599, 2022). "Moreover, it has been shown that NRP‐1 stimulates growth of different tumour types, while NRP‐1 silencing suppresses cancer cell growth." (PMID 34252269, 2022).
tumor (continued). "The results showed that m6Ascore was negatively correlated with the expression of TMIGD2, TNFRSF18, TNFRSF25, TNFRSF4, TNFRSF8, and NRP1, indicating that the poor prognosis of high-m6Ascore patients might be due to the tumor immunosuppressive microenvironment." (PMID 36313417, 2022). "Currently, NRP1 is known as a critical barrier for anti‐tumor immunity." (PMID 36062301, 2022). "The blockade of NRP1-VEGFR2 interaction led to restriction of tumor growth and angiogenesis in a mouse model of CRC, while targeting NRP1 with a specific antagonist prevented migration induction in CRC cells adapted to the treatment with the VEGFR-targeting drug sunitinib." (PMID 35884516, 2022). "Ablation of Nrp1 in T cells led to significantly reduced tumor volume when compared to WT controls." (PMID 36203599, 2022). "This phenomenon may occur in TAMs, with NRP2-expressing cells residing within an inhospitable TME and NRP1 expressing TAMs located in regions with supportive conditions or having more recently emigrated to the tumor." (PMID 35651620, 2022). "Moreover, NRP1 overexpresses in several tumor types, including HCC, CCA and CRC, being related to a malignant phenotype and promotion of cell migration." (PMID 35884516, 2022). "NRP1 acts as a co-receptor for some extracellular ligands to take part in a variety of physiological and pathological processes, including angiogenesis, cardiovascular development, immunity, cell migration, axonal guidance, and tumor development." (PMID 36338984, 2022). "In endothelial and tumor cells, NRP1 was shown to connect with β1 integrin subunits." (PMID 36204684, 2022). "In a high-risk cohort, a new-found checkpoint NRP1 (neuropilin-1) was reported as an immune response suppressor to cancer gathered higher expression, as well as CD276, which was proven to participate in tumor immune evasion in HNSCC." (PMID 35432535, 2022). "Finally, meta-regression was also performed to assess the heterogeneity sources related to the role of NRP1 overexpression in tumor pathogenesis." (PMID 35884516, 2022). "Likewise, simultaneous depletion of both endothelial NRP1 and NRP2 resulted in an equivalent loss of colocalized phosphorylated-VEGFR-2Y1175 expression from tumor vessels." (PMID 36970722, 2022). "Finally, we show that NRP1 acts as a central hub for the aberrant activation of the RAS-MAPK pathway via EGFR and PDGFR activation to drive aggressive tumor progression, a hallmark of all claudin-low subgroups." (PMID 35078508, 2022). "Genetically targeting Nrp1 impedes the entry of TAMs into hypoxic regions, which are retained in the normoxic regions instead, preventing immunosuppression and angiogenesis and promoting anti-tumour immunity." (PMID 36497148, 2022). "As NRP1 inhibition decreased spheroid formation, we speculated that NRP1 may enhance the in vivo tumor-initiating potential of claudin-low cells." (PMID 35078508, 2022). "Further, NRP‐1 has been proposed to modulate immune cell activities in tumour immune surveillance." (PMID 34252269, 2022). "We also analyzed the relationship between tissue-specific NRP1 expression and overall survival (OS), as well as tumor immune environment at a pan-cancer level, providing a comprehensive insight into the relationship between the vulnerability to SARS-CoV-2 infection and tumorigenesis." (PMID 36338984, 2022). "Conversely, mice lacking Nrp1 in macrophages (LysM-Cre;Nrp1L/L) exhibited reduced tumor progression in models of non-CNS carcinomas: specifically, the loss of Nrp1 in macrophages resulted in 55% fewer lung metastases and 60% smaller tumors." (PMID 36203599, 2022). "Antitumor immunity requires the production of long-lasting tumor-specific T cells, which may be boosted by blocking NRP1." (PMID 35794981, 2022).
tumor (continued). "Beyond Sema4F, multiple axon-related molecules, classified for their function in tumor axonogenesis, such as Bmp7, Robo1, Fibronectin, or Nrp1, and the synaptic adhesion molecule IGSF11/VSIG-3 are regulated upon TGFβ−mediated EMT induction, hnRNP E1 silencing, or Platr18 overexpression." (PMID 34810279, 2022). "In fact, both SP1 and HIF-1α positively regulate NRP1 expression in tumor cells." (PMID 35600336, 2022). "However, in Lewis lung cancer, Sema3A binding to Nrp1 and PlexinA1/PlexinA4 coreceptors promotes tumor growth by TAM infiltration and pro-tumorigenic function in hypoxic areas." (PMID 35155237, 2022). "The fusion protein tTF-EG3287 could target tumor blood vessels by binding to highly expressed NRP-1, thereby anchoring tTF to the surface of the endothelial cell membrane." (PMID 35858896, 2022). "Changes in phospho p42/44 staining in Vesencumab-treated tumors suggested that NRP1 may regulate the RAS/MAPK axis in tumor vascular walls and endothelial-like cells." (PMID 35078508, 2022). "Our data demonstrated that GPX8 was correlated with mRNA expression of immune markers of CD8+ T cells (CD8B), CD4+ T cells (CD4), T cells (CD3D), macrophages (CD68 and ARG1), neutrophils (ITGAM and CCR7), dendritic cells (NRP1), NK cells (B3GAT1), and tumor-associated fibroblasts (FAP)." (PMID 36061208, 2022). "We therefore examined whether VEGFR-2 signaling would be perturbed in tumor vasculature depleted for NRP1 and NRP2 by measuring VEGFR-2 and phosphorylated-VEGFR-2Y1175 localization to endomucin+ vessels." (PMID 36970722, 2022). "Among included studies, five different ones performed with HCC patients evaluated the potential association of high NRP1 levels with tumor development by comparing tumor tissue to non-tumor adjacent tissue." (PMID 35884516, 2022). "In addition to enhancing the functions of Tregs, NRP1 can also inhibit the immune memory generated by CD8+ T cells in the process of anti-tumor immunity, and anti-NRP1 treatment can improve the efficacy of anti-PD-1 immunotherapy." (PMID 36406134, 2022). "Either NRP-1 or NRP-2 or both are expressed in nearly all tumor cells." (PMID 35052853, 2022). "Inhibition of NRP1 suppresses tumor migration and angiogenesis." (PMID 35600336, 2022). "In all tumor models studied, the infiltrating Tregs were similarly Nrp1- Helios+." (PMID 35523809, 2022). "Another study has demonstrated that blockage of Sema3A/Nrp1 could also enhance anti-tumor response by increasing M1-Mφs and decreasing M2-Mφs in colorectal carcinoma." (PMID 35155237, 2022). "In the context of cancer, NRP1 could participate in Tregs recruitment to the tumor by acting as a coreceptor for VEGF." (PMID 33924428, 2021). "The neuropilins NRP1 and NRP2 are multifunctional glycoproteins that have been implicated in several cancer-related processes including cell survival, migration, and invasion in various tumor types." (PMID 34239847, 2021). "Furthermore, the poor prognosis of patients with NRP1 overexpression in their tumor cells is due to the involvement of NRP1 in tumor progression and tumor growth." (PMID 34277411, 2021). "Similarly, LinTT1 and TT1 first bind to p32, a mitochondrial protein aberrantly expressed on the cell surface of tumoral cells and are then cleaved by proteases expressed by the tumor cells, allowing them to interact with NRP-1." (PMID 34683924, 2021). "Moreover, it was reported that protein kinase LKB1 promoted Rab7-mediated NRP-1 degradation and inhibited the angiogenesis in tumor cells." (PMID 34695807, 2021). "Inhibition of NRP-1 would help control tumor malignancy in radiation-surviving NSCLC." (PMID 34698100, 2021). "NRP1 may also play a role in the regulation of immunogenicity of tumor cells, highlighted by the correlation between NRP1 and PDL-1." (PMID 34277411, 2021). "Therefore, TME-derived VEGFR2 and NRP1 is likely being expressed by endothelial cells surrounding the HCC tumor in order to promote a new vascular network for the xenograft." (PMID 33995488, 2021).